FBXW7 (F-box and WD repeat domain containing 7)
Diseases named in the same sentence as FBXW7 in open-access papers (continued):
Sharing a sentence is not in itself a finding about the gene and the disease.
cancer (continued). "In the current research, we found that the tumor suppressor gene FBXW7 is usually mutated and inactivated after the occurrence of cancer, and the body sends instructions for gene repair, which allows the antioncogene lncRNA to recruit and bind genes or proteins that can repair DNA damage." (PMID 35273678, 2022). "Consistently, FBXW7 is frequently lost or mutated in various types of cancers." (PMID 33670113, 2021). "It has been reported that rapamycin could inhibit FBXW7 loss-induced epithelial-mesenchymal transition and cancer stem cell-like characteristics in CRC cells." (PMID 34217244, 2021). "Previous reports have suggested that FBXW7 mutations could improve cancer-initiating cell activities through the NOTCH signaling pathways." (PMID 35712679, 2021). "Moreover, loss of FBXW7 has been found to be a key prognostic factor promoting resistance to gamma‐secretase inhibitors (GSIs) in certain cancer types." (PMID 33822486, 2021). "Importantly, FBXW7 deletion or loss-of-function mutations from patient-derived cancer cells impair the MCL-1 degradation and result in resistance to chemotherapy drugs." (PMID 32907612, 2020). "In addition to loss-of-function mutations in the substrate binding domain of FBXW7, mutations of FBXW7 substrates have been found to be associated with cancer and to concentrate in the CPD." (PMID 32429232, 2020). "Ubiquitin ligase FBXW7 is commonly mutated or functionally inactivated in human cancers." (PMID 32907612, 2020). "F-box/WD repeat-containing protein 7 (Fbxw7) is frequently mutated in human cancers of many types." (PMID 32140077, 2020). "Notably, FBXW7 ubiquitinates and degrades mTOR, and loss or mutation of FBXW7 increases the sensitivity of cancer cells and mouse models to rapamycin." (PMID 33291075, 2020). "Human homologs of Met30 (β-TrCP) and Cdc4 (Fbxw7) have also been implicated in cancers." (PMID 32032354, 2020). "Downregulation or mutation of Fbxw7 leads to the development of various cancers in humans." (PMID 31371703, 2019). "Hence, perturbation of the expression of FBXW7 is considered as one of the major causes of cancer development and progression." (PMID 30791487, 2019). "In addition, it is possible that co-mutation of Kras with certain Fbxw7 mutations transforms cells and drives cancer development in vivo in a cell-type dependent manner." (PMID 31748650, 2019). "Understanding the critical role of FBXW7 in RCC may lead to the development of a novel diagnostic marker for this type of cancer." (PMID 29097832, 2017). "The FBXW7 gene locus 4q32 is deleted in a third of cancers and copy loss occurs in 15%." (PMID 28829765, 2017). "Therefore, the loss of FBXW7 function results in accumulation of its substrates, which leads to oncogenesis and progression of multiple cancers including CRC." (PMID 28424412, 2017). "The tumor suppressor gene FBXW7 is deleted and mutated in many different types of human cancers." (PMID 26575021, 2015). "Previous studies revealed FBXW7 mutations in approximately 6% of cancer patients." (PMID 24586741, 2014). "FBXW7 is often mutated in a subset of human cancers including CRC." (PMID 25275295, 2014). "Therefore, the altered expression of FBXW7 is recognised to be one of the major causes of carcinogenesis or cancer development." (PMID 22108521, 2012). "Accordingly, mutation of human FBXW7 has been implicated in numerous cancers." (PMID 22554084, 2012). "Elucidation of the mechanisms by which this and other Fbxw7 genetic variants act may allow us in future studies to recognize patients who are at high risk of cancer development, or who may be more likely to respond to therapies targeted at this pathway." (PMID 22348067, 2012).
cancer (continued). "Furthermore, targeted disruption of the Fbxw7/hCdc4 gene has been shown to result in enhanced genomic instability, a hallmark of cancer cells." (PMID 21122106, 2010). "In addition, dimerization of FBXW7 may play important roles in cancer cells whereby one copy is mutated." (PMID 35346215, 2022). "Furthermore, for another F-box protein, FBXW7, subcellular mislocalization and exclusion from nucleus has been suggested as the key functional impairment for different somatic variants implicated in various cancers." (PMID 34505148, 2022). "Regardless of MYC, a genetic screen in Drosophila identified that FBXW7 depletion impaired autophagy, which could explain the accumulation of dysfunctional mitochondria that is seen in FBXW7‐deficient cancer cells, rendering them sensitive to therapies further compromising mitochondrial function." (PMID 35861150, 2022). "Interestingly, Fbxw7 localizes to human chromosome 4q31.3, which is deleted in about 30% of human cancers and somatic mutations in Fbxw7 have been detected in tumors of diverse tissue origin, including blood, breast, bile duct, colon, endometrium, stomach, lung, bone, ovary, pancreas and prostate." (PMID 32032354, 2020). "In-depth study of Fbxw7 mutations will not only contribute to the diagnosis of cancer using Fbxw7 mutation as biomarkers, but also help in the development of targeted therapeutics for these mutations, which has positive implications for the prevention of cancer and individualized treatment." (PMID 26886596, 2016). "For instance, nine of our candidate cancer genes were also contained in the Cancer Gene Census list, which comprises 487 genes causally linked to cancer, representing a highly significant enrichment (Abl2, Braf, Fbxw7, Foxp1, Ipo11, Mllt3, Fas, Pten, and Nf1; p<0.0002, Fisher’s exact test)." (PMID 23940809, 2013). "FBXW7 is one of the most frequently dysregulated proteins of the ubiquitin-proteasome system in various human cancers." (PMID 41869454, 2026). "A defining feature of USP28 is its antagonistic relationship with the E3 ubiquitin ligase FBXW7, stabilizing oncoproteins such as c-Myc and NOTCH1, a mechanism particularly relevant in cancers characterized by FBXW7 depletion." (PMID 40858801, 2026). "In adenomyotic epithelium, we identified somatic mutations in cancer-associated genes such as KRAS (34.1%), PIK3CA (12.2%), ARID1A (12.1%), and FBXW7 (9.8%) with high mutant allele frequency." (PMID 40679511, 2025). "As a well-studied E3 ligase in cancer biology, FBXW7 was recently reported to be involved in lipid and glucose metabolism via the degradation of Fetuin-A or REV-ERBα in the liver." (PMID 39747664, 2025). "In vitro, ex vivo, and in animal models of metastasis, the FBXW7-Zinc-finger E-box-binding homeobox-2 (ZEB2) axis affects critical characteristics of cancer cells, including stemness/dedifferentiation, chemoresistance, and cell migration." (PMID 41373479, 2025). "FBXW7 is a key tumor suppressor whose dysregulation contributes to malignant progression across multiple cancer types." (PMID 40370434, 2025). "This cluster contained mutations in representative cancer-associated genes such as KRAS, ARID1A, PIK3CA, and FBXW7." (PMID 40679511, 2025). "In this study, we report that glutamine modulates the tumor suppressor F-box and WD repeat domain-containing 7 (FBW7) to promote cancer cell proliferation and survival." (PMID 40338031, 2025).
cancer (continued). "This Pin1-mediated reduction in FBXW7 expression contributes to tumorigenesis, highlighting Pin1 as a potential therapeutic target in cancer." (PMID 40534867, 2025). "FBXW7 is a well-established cancer suppressor gene that specifically controls proteasomal degradation and destruction of many key oncogenic substrates." (PMID 39749199, 2024). "Intriguingly, NLRP3 and FBXW7 are consistently identified as miR-223 targets when the miRNA acts as an oncosuppressor or an oncogene, respectively, in different cancers." (PMID 39125761, 2024). "Until now, only a few studies have explored the role of FBXW7 in the regulation of CSCs in several cancers, such as colorectal CSCs, lung CSCs, and live CSCs." (PMID 38268032, 2024). "FBXW7 has been identified as a cancer suppressor gene that frequently malfunctions in a variety of human cancers." (PMID 39749199, 2024). "The activation of the KRAS-ERK pathway in PC further suppresses FBXW7 expression, facilitating cancer progression." (PMID 39749199, 2024). "We recently demonstrated the transcriptional repression of FBXW7 by the three-dimensional (3D) spheroid formation of several cancer cells." (PMID 38892210, 2024). "miR-223 is overexpressed in cancer cells and can downregulate the expression of FBXW7, contributing to the development of resistance to multiple anticancer drugs." (PMID 39748950, 2024). "Nanog is a possible substrate of FBXW7-mediated protein degradation and leads to chemoresistance in cancer." (PMID 38892210, 2024). "Previous studies reported that CEBPD negatively regulated FBXW7 gene expression in cancer cells and was essential for the acquisition of cancer stemness properties." (PMID 38892210, 2024). "FBXW7 plays a pivotal role in various processes, including cancer cell proliferation, metastasis, invasion, apoptosis, and treatment resistance." (PMID 39749199, 2024). "miR223 is mostly known as a target for FBXW7 and negatively correlates with FBXW7 expression in cancer cells." (PMID 38892210, 2024). "Oncogenic microRNAs (miRNAs) promote cancer development by targeting tumor suppressor genes, and miRNAs such as miR223 and miR135a play an essential role in the function of FBXW7 in cancer cells." (PMID 38892210, 2024). "This upregulation promoted cancer cell proliferation by suppressing FBXW7 transcription and protecting the c-Jun protein from FBXW-7-mediated ubiquitination and degradation." (PMID 38216914, 2024). "Given the carcinogenic effects of various regulatory proteins and molecules, FBXW7 has a broad and profound role in the occurrence and progression of human cancer." (PMID 39749199, 2024). "As FBXW7 plays a role as a cancer suppressor, an agonist of the FBWX7 E3 ligase complex, oridonin degrades c-Myc and induces apoptosis in leukemia and lymphoma cells." (PMID 37176148, 2023). "FBXW7, one of the F-box proteins of the SCF complex, is encoded by a gene that appears frequently mutated or suppressed in human cancers." (PMID 36477079, 2023). "Fbxw7 suppresses cancer niche proliferation through ubiquitination and degradation of Notch pathway." (PMID 36971192, 2023). "In this study, we review the involvement of imbalanced FBXW7 in the development of therapeutic resistance in cancer." (PMID 38027013, 2023).
cancer (continued). "A tumor suppressor factor named F-box and WD repeat domain-containing 7 (FBW7) recognizes substrates as part of the Skp1-cullin 1-F-box (SCF) E3 ubiquitin ligase complex, which catalyzes the degradation of many cancer-causing proteins." (PMID 36831377, 2023). "Development of drugs that modulate regulatory factors upstream of FBXW7 and substrates downstream of FBXW7 for use in cancer cells with FBXW7 inactivation can be considered." (PMID 38027013, 2023). "Overall, this review aims to explore the function of FBXW7 and its specific effects on drug resistance in cancer cells." (PMID 36998461, 2023). "Complete ablation of FBXW7 expression can desensitize cancer cells and prevent cancer cell death, indicating that some FBXW7 activity is required for effective anti-cancer therapy." (PMID 37408248, 2023). "miR-223 is overexpressed in cancer cells and participates in the development of resistance to multiple anticancer drugs by down-regulating FBXW7 expression." (PMID 38027013, 2023). "This evidence demonstrates that the SCF complex, especially that of CUL1 and FBXW7, is worthy of continuous investigation for the development of cancer-targeting therapy." (PMID 37760968, 2023). "Exosomes of the cisplatin resistant GC cells have also been found to enhance cisplatin resistance by targeting FBXW7 with miR-500a-3p in vitro and in vivo, but FBXW7 can rescue cisplatin resistance by inhibiting cancer stem cells properties." (PMID 36998461, 2023). "Other molecules, such as FOXA1, SETD2, Hes5, C/EBP-δ, PRMT5, METTL3, Piwil1, PLK1, ERK1/2, and a series of miRNA, indirectly modulate the sensitivity of cancer cells to drugs by regulating FBXW7." (PMID 36998461, 2023). "The finding that FBXW7 is an upstream regulator of CCL2 expression also has implications for the development of new treatment strategies for cancer patients." (PMID 37208442, 2023). "FBXW7 mediates the ubiquitination and hydrolysis of numerous oncoproteins, including key factors involved in cancer drug resistance." (PMID 38027013, 2023). "The loss of function (mutation or deletion) of tumor suppressor gene FBXW7 and the overexpression of c-MYC oncoprotein are related to the expression level of PD-L1 and poor prognosis in some malignant tumors." (PMID 36998461, 2023). "FBXW7 was decreased and mutated in ESCC, and elevated MAP4 increased activation of the ERK pathway, which enhanced the characteristics of cancer cells." (PMID 36991467, 2023). "In human cancers, FBXW7 is often inactivated via genetic and epigenetic mechanisms and post-transcriptional modifications." (PMID 37408248, 2023). "FBXW7 is a topic of increasing interest in cancer research, as it serves a role in protein ubiquitylation and proteosome-mediated degradation, which is responsible for the regulation of multiple crucial oncogenes." (PMID 37064111, 2023). "FBXW7, as a ubiquitin ligase, can combine with lots of cancer-related factors, including c-Myc, cyclin E and mTOR." (PMID 37404825, 2023). "In this respect, it is interesting to note that ubiquitin ligases that modulate AurkA stability, for example, Fbxw7 and VHL, are frequently mutated in cancer (references 22, 50 and references therein)." (PMID 36797043, 2023). "As a connector of DDR and metabolism, targeting FBXW7 makes a lot of sense as a therapeutic intervention for targeting cancer, tuning DDR and metabolic programs at the same time." (PMID 37176148, 2023). "We selected representative proteins, NEDD4, APC/CCDH1, and FBXW7, which have been extensively studied in cancer metabolism and are also involved in the DDR pathway." (PMID 37176148, 2023). "In practice, FBXW7 figures as a double-edged sword impacting tumorigenesis, especially its role in maintenance of cancer cell stemness." (PMID 35515121, 2022). "FBXW7, a critical suppressor of human cancers, is a direct target of miR-25-3p, as determined by bioinformatics analysis and the luciferase reporter assay." (PMID 35295711, 2022).
cancer (continued). "In this study, we illustrated the role of ZC3H15 that stabilized c-Myc protein level via inhibiting FBXW7 transcription to promote cancer progression." (PMID 35064102, 2022). "Another study demonstrated that FBXW7 has an intimated relation with chromatin remodeling through whole-exome sequencing of 57 cancers." (PMID 35814468, 2022). "Among these negative-selected PCGs are F-box only protein 11 (FBXO11) and F-box/WD repeat-containing protein (FBXW7), which have been previously demonstrated to be involved in cancer immunology." (PMID 36475797, 2022). "In some instances, cancers cells express low levels of FBXW7 protein because of pathologic rapid turnover." (PMID 35346215, 2022). "Apart from involvement in cancer, downregulation of FBXW7 by miR-322 demonstrates a possible curing method to protect myocardium from ischemia/reperfusion injury." (PMID 35814468, 2022). "We demonstrated that this cancer-derived CHD6 mutant is resistant to FBXW7-mediated degradation, suggesting that its continual stability/activity is critical in mediating tumorigenesis." (PMID 36473865, 2022). "Future studies will determine if targeting FBXW7 solely or using dual therapies that target FBXW7 and/or downstream or parallel pathways, is more beneficial to cancer treatment." (PMID 35346215, 2022). "In fact, PRMT5 expression is inversely correlated with FBXW7 and closely associated with aberrant MYC function in human cancers." (PMID 35346215, 2022). "In support of this view, analysis of survival data from the Genomics Data Commons (GDC) portal revealed that low levels of FBXW7 expression significantly correlated with poor survival in cancer patients undergoing any type of therapy." (PMID 35861150, 2022). "We here systematically addressed the impact of FBXW7 deficiency in the response to anticancer therapies, and identify a vulnerability that can be exploited to target FBXW7‐mutant cancer cells." (PMID 35861150, 2022). "For the application of the cancer evolutional model, we identify potential evaluation therapeutic targets, such as MYO18A, and FBXW7 genetic mutations in CRCs." (PMID 36009026, 2022). "F-box and WD repeat domain-containing 7 (Fbw7) is a ubiquitin ligase that acts an important role in cancer by targeting several key proteins for proteolysis." (PMID 35359405, 2022). "FBXW7 is frequently inactivated in human cancers through genetic and epigenetic mechanisms, along with post transcriptional modifications." (PMID 35346215, 2022). "FBXW7 (F-box and WD repeat domain–containing 7) is usually deemed as a negative regulator of human cancers and is the most crucial F-box protein in E3 ligase so far." (PMID 35814468, 2022). "More work should be done to investigate the function of FBXW7 in various cancers for so many proteins can be ubiquitinated by SCFFBXW7." (PMID 35814468, 2022). "FBXW7 is a key participant in the ubiquitin-proteosome system and negatively regulates the downstream cancer-related genes." (PMID 35712679, 2021).